AFP (alpha fetoprotein)
Diseases named in the same sentence as AFP in open-access papers (continued):
Sharing a sentence is not in itself a finding about the gene and the disease.
cancer (continued). "While TSAs, including alpha-fetoprotein (AFP), glypican-3 (GPC3), and melanoma-associated gene 1 (MAGE-1) in HCC, are predominantly cancer-centric, their presence, albeit in lower quantities, is not exclusive to cancer cells." (PMID 39295859, 2024). "CEA, AFP, and PSA cancer biomarkers were detected from serum samples." (PMID 36979600, 2023). "Additionally, it has shown that it is capable of the concurrent detection of cancer biomarkers, such as carcinoembryonic antigen (CEA) and alpha-fetoprotein (AFP), in actual human serum." (PMID 36831931, 2023). "This AbTCR + co-stimulatory T cell therapy showed potent activity against AFP-positive cancer cell lines in vitro and an in an in vivo model and undetectable activity against AFP-negative cells." (PMID 35840635, 2022). "In addition, the N-terminal heptapeptide of AFP (AFP14-20) interacts with the consensus motif (CxxGY/FxGx) of EGF family proteins, including the well-known cancer-related factor EGF." (PMID 36496998, 2022). "In conclusion, we developed a clinically feasible ECLIA method for measuring IgM-free AIM in serum and demonstrated that IgM-free AIM is a more precise biomarker for HCC than the conventional biomarkers, AFP or DCP, for NASH-HCC, as well as for HBV- or HCV-related HCC, even in early cancer stages." (PMID 34981443, 2022). "SATB2 may be a driving force for developing cancer stem‐like phenotypes in damaged hepatocytes where induction of stem cell markers (CD44, CD90, EpCAM, AFP and LGR5) and pluripotency maintaining factors (POU5F1/Oct4, Sox‐2, Nanog and KLF4) was prominent." (PMID 35152538, 2022). "AFP levels in patients with elevated AFP were stable during follow-up without liver injury or cancer development." (PMID 35862314, 2022). "The observation that knockdown of FUNDC2 also reduces expression of AFP, an indicator of HCC malignancy, and a marker of cancer stem cells, suggests that the cancer stem cell compartment may be more susceptible to inhibition of FUNDC2." (PMID 35710796, 2022). "Serum AFP is frequently increased in the presence of HCC and within our study group, we did not encounter AFP levels below 100 ng/ml, suggesting once again that AFP represents a powerful screening tool for this type of cancer." (PMID 35497085, 2022). "Furthermore, HCC patients with high AFP levels, low OS and DSS rates, and advanced cancer stages also showed higher EXO1 levels." (PMID 35769911, 2022). "Some established cancer markers, such as α-fetoprotein (AFP) and carcinoembryonic antigen (CEA), are usually expressed at the embryonic stage during individual development, silenced after birth, and re-expressed in cancer patients." (PMID 34880864, 2021). "Moreover, an updated study indicated that GP73 directly interacted with AFP and facilitated its secretion, which led to EMT of recipient cells of AFP and promoted immune escape of cancer cells." (PMID 34950590, 2021). "PM patients with malignancy showed a significantly higher proportion of abnormal CEA and AFP results than patients without malignancy (p = 0.03 and p = 0.00, respectively)." (PMID 33633147, 2021). "CEA and AFP are cancer protein biomarkers that are not specific to PCa as they can be found in a variety of cancer types." (PMID 34372259, 2021). "Unlike conventional cancer biomarkers, including carcinoembryonic antigen and AFP, exosomal miRNAs can transfer their functions to target cells and modulate cell signaling." (PMID 34200243, 2021). "Although the AFP and β-hCG levels in FIF may be elevated, persistent high levels are more likely to be a sign of malignant tumors." (PMID 34109141, 2021).
cancer (continued). "Although the details of the AFP-binding receptor structure are not known, many studies have shown that cancer cells take up AFP through AFP-binding receptors." (PMID 33898423, 2021). "GCT, despite their characteristically low mutational burden and lack of neoantigens, express proteins characteristic of their embryonal origin such as Alpha-fetoprotein (AFP) with documented MHC-I-restricted, AFP-directed antineoplastic T cell responses in other AFP-positive cancers." (PMID 32438548, 2020). "The combination of CTC counts with serum AFP levels and Tg should decrease false-negative rates and is recommended for disease monitoring of patients with the respective cancer types who are undergoing treatment." (PMID 32071283, 2020). "False AFP elevation in GCTs refer to elevated serum AFP levels when there is no clinical evidence of any malignant tumor activity, which is rarely reported in MOGCTs." (PMID 31836006, 2019). "However, its low expression in early stage cancers makes it a poor biomarker for large-scale HCC screening, especially since 30% of patients with HCC continuously have normal AFP levels." (PMID 31258835, 2019). "The serum cancer biomarkers Ca125, Ca153, Ca199, HE4, CEA and AFP were within normal limits." (PMID 31139268, 2019). "Second, there may have been testing, reporting, and interpretation differences in AFP values between hospitals both within and across the SEER cancer registries." (PMID 31517445, 2019). "When AFP was incubated with DCs from human peripheral blood, the cells were found to express Caspase-3 and p38-MARK, which would induce apoptosis and inhibit the maturation of DC cells, thus resulting in the immune escape of cancer cells." (PMID 29805966, 2018). "As expected, AFP levels increase close to the time of cancer diagnosis though the change was not statistically significant (p = 0.067)." (PMID 30169533, 2018). "Although boys with an elevated AFP level were inclined to have a malignant tumor and undergo radical orchiectomy, no significance was detected in this study." (PMID 28347316, 2017). "For example, although the sensitivity and specificity were not very high enough to gain grade 1 recommendations, the serological markers CA125, CA19-9, AFP and PSA are biomolecules decorated with glycans that are commonly overexpressed by a number of cancer types." (PMID 28052004, 2017). "Since our molecular analyses indicated an activation of stemness in the SL region, we next assessed the gene expression levels of specific HCC/differentiation markers (AFP, GPC3, albumin) as well as the selected (cancer-) stemness markers (EpCAM, CD133, CK19) and pluripotency genes (NANOG)." (PMID 28415775, 2017). "The immunohistochemical findings usually indicate that these cancers are positive for AFP and HeP and negative for Cal and MC." (PMID 27069474, 2016). "However, the patient had normal levels of alpha-fetoprotein (AFP), carcinoembryonic antigen (CEA), cancer antigen 19-9 (CA19-9), gamma-glutamyltransferase (GGT), and lactate dehydrogenase (LDH)." (PMID 27669688, 2016). "A multiplexed electrochemical platform of paper based immunosensors was developed by Wu and co-workers for the detection of cancer biomarkers, namely carcinoembryonic antigen (CEA), alphafetoprotein (AFP), cancer antigen 125 (CA125) and carbohydrate antigen 153 (CA153)." (PMID 27690119, 2016). "In HCC rats exposed to PEMFs, a significant decrease in AFP level (AFP is a serum glycoprotein often elevated in HCC patients and used as a carcinoma marker in the clinic) was reported together with a slight improvement in dielectric properties of liver tissue." (PMID 27748048, 2016). "This study screened 10,000 adult people and recruited 1,826 HBsAg positive adults with normal liver function test, negative serum alpha-fetoprotein, no personal history of cancer, and no use of prescribed medications, in Guangxi, China." (PMID 26180594, 2015).
cancer (continued). "Except for one patient (0.91%) in the transplantation group with an increase in CA-153, no abnormalities in brain CT or MRIs, routine and biochemical blood indices, or cancer biomarkers (CA-153, NSE, ALP, AFP, CEA, CA242, CA125, and CA199) were identified during follow-up studies." (PMID 26240570, 2015). "In this case, the weakly positive immunohistochemical AFP and normal serum AFP show no significance in differentiating malignant tumors." (PMID 24767257, 2014). "Among TFs that control AFP gene transcription in a cooperative fashion stands NANOG, a stemness factor expressed in pluripotent and cancer stem cells, and which is one of the major protein protagonists involved in the cell allostatic decision between self-renewal and differentiation." (PMID 25502816, 2014). "We do not expect GP73 to complement the results of AFP, as we studied a large and unique group of patients with benign and malignant solid liver tumors." (PMID 25033446, 2014). "We confirmed that the prognosis was worse for patients with than without AFP who were matched by cancer stage." (PMID 23382965, 2013). "It is important to note that genetically, AFP negative cancers are thought to be fundamentally different than AFP positive tumors." (PMID 24564861, 2013). "The cytopathic effects were lower in the AFP-negative cancer cell lines 786-O, A549, and the normal cell line MRC-5, as expected." (PMID 22040050, 2011). "While this data is encouraging, the sensitivity of AFP is not good enough for it to be used in isolation, as over a third of cancers will be missed." (PMID 18638391, 2008). "Of interest lately is the increasing documentation of AFP-producing extrahepatic hepatoid/non-hepatoid carcinomas that have a propensity for vascular invasion and liver metastases." (PMID 15941489, 2005). "The current study also demonstrated that AGTAG model has better efficacy than AFP in the screening of HCC in healthy people, which is strong evidence of the efficacy of this HCC screening method in the real world and can provide a valuable reference for future pan-cancer blood screening programs." (PMID 40060905, 2025). "Interestingly, while AFP failed to correlate with TNF-α among cancer patients, it approached a moderate correlation (rho = 0.383, p = 0.0956) in controls, though still not significant." (PMID 40299527, 2025). "In addition, the downregulation of stem cell surface markers (AFP, EpCAM, CD133, CD24, and ALDH1A), Wnt and Notch pathway genes, and drug resistance genes was observed, indicating that the EpCAM-apt-Dox targets and impairs cancer stem like cell properties." (PMID 39192365, 2024). "Additionally, the clinicopathological characteristics of the patients indicated significant correlations between the HPSM groups and multinodularity, Cancer of the Liver Italian Program (CLIP) staging, Alpha-fetoprotein (APF), and survival times of HCC patients." (PMID 38244582, 2024). "In addition, AFP could both activate the PI3K/P-AKT/mTOR cellular pathway and stimulate the cancer cell growth by binding with phosphatase and tensin homolog (PTEN)." (PMID 38408930, 2024). "AFP could serve as an ideal protein for the targeted transport of toxin to cancer cells expressing the AFPR since AFP is selectively endocytosed by cancer cells but not by normal adult cells." (PMID 37016369, 2023). "Moreover, AFP levels remain normal (AFP level < 20 ng/mL) in up to 30% of advanced cancer cases but are elevated in some individuals without HCC, leading to high negative and false-positive rates." (PMID 38003232, 2023). "Additionally, AFP-initiating pulmonary hepatoid adenocarcinoma is a rare cancer that is not yet been fully studied." (PMID 37444523, 2023). "Elevated AFP levels were stable without liver injury or cancer development." (PMID 35862314, 2022).
cancer (continued). "Interestingly, this is the first report that AFP-siRNA-incorporated PLGA nanoparticles possessed a synergistic effect with angiogenesis inhibitor drug to inhibit the viability of HepG2 cancer cells without apoptotic cascade activation." (PMID 36293521, 2022). "Moreover, the area under the receiver operating curve for IgM-free AIM was greater than that for conventional HCC biomarkers, alpha-fetoprotein or des-γ-carboxy prothrombin, regardless of the cancer stage." (PMID 34981443, 2022). "Furthermore, serum AFP levels remain normal in 15–30% of advanced HCC, as, in our case, stressing the importance of finding other circulating markers capable of detecting AFP-negative cancer patients." (PMID 35743734, 2022). "In addition, most of the broadly validated cancer biomarkers are biofluidic glycoproteins, including but not limited to alpha-fetoprotein (AFP), CA19-9 (cancer antigen 19-9), CA125, CA15-3, carcinoembryonic antigen (CEA), and prostate-specific antigen (PSA)." (PMID 35159390, 2022). "Alpha-fetoprotein is therefore incorporated into several prognostic scoring systems [the Cancer of the Liver Italian Program (CLIP), the Chinese University Prognostic Index (CUPI), Groupe d'Etude et de Traitement du Carcinoma Hépatocellulaire (GRETCH), and French scoring system AFP model." (PMID 35186078, 2022). "Combined with the current research, the use of antibodies to AFP in cancer is not very practical." (PMID 34680245, 2021). "Interestingly, early after the beginning of sorafenib treatment, a further increase of PIVKA-II not correlated with AFP and cancer cells kinetics was observed in most of the cases." (PMID 33922938, 2021). "The serum AFP level of patients with malignant lesions was higher than that of patients with inflammatory lesions (P < .05), whereas the WBC level and EOS% level of patients with inflammatory lesions were significantly higher than that of patients with malignant lesions (P < .05)." (PMID 32017229, 2020). "Although AFP was overexpressed in our new HTC cancer cell line, it was not expressed in TW-1." (PMID 33322441, 2020). "Therefore, the HCC patients with AFP negative or weak positive in serum is usually consistent with the characteristics of high differentiated cancers." (PMID 29805966, 2018). "Further, EGb could decrease the levels of alpha-fetoprotein (AFP), glypican-3 (GPC-3) and carcinoembryonic antigen (CEA) in HCC rats, suggesting that the anti-cancer efficacy of EGb was induced through its anti-proliferative and apoptotic properties in the HCC animal model." (PMID 29344418, 2017). "Therefore, for boys less than 1 year old, an elevated level of AFP was not indicative of a malignant tumor." (PMID 28347316, 2017). "However, current treatments targeting AFP are not reproducible and do not provide complete protection against cancer." (PMID 27713135, 2016). "However, another study released alongside showed that depletion of ATOH8 reprogramed non-cancer stem cells into cancer stem cells by directly releasing AFP, CD133, OCT4 and NANOG." (PMID 27049918, 2016). "This inhibition may have a negative effect on cancer cell proliferation because AFP is known to have a proliferative effect on cancer cells." (PMID 25822740, 2015). "Although serum AFP levels have been high in all previously reported cases, it is important to remember that serum AFP levels may not rise in the early stages of AFP-producing cancer." (PMID 25962419, 2015). "Combining this observation with the facts that telomerase is responsible for cell immortalization in more than 85% of cancers, including HCC, and that its mRNA is detected in the serum of patients with HCC, we investigated the possible interaction between telomerase and AFP." (PMID 25822740, 2015).
cancer (continued). "The same technology could be extended to other types of proteins especially cancer markers such as Ca 15-3, 27, 125, bladder tumor antigen (BTA), carcinoembryonic antigen (CEA), alpha-fetoprotein (AFP), IL-10, as well as small molecules, as long as the required suitable aptamers are made available." (PMID 26102488, 2015). "The aptamer could be used as a probe in AFP immunofluorescence imaging in HepG2, one AFP positive cancer cell line, but not in A549, an AFP negative cancer cell line." (PMID 26497223, 2015). "Normal alpha-fetoprotein levels rule out cancer originating from the liver." (PMID 25250798, 2015). "Moreover, the CTLs specifically lysed the AFP-positive carcinoma cells, while the AFP-negative carcinoma cells were not lysed, indicating that the CTL response was antigen-specific." (PMID 23170121, 2012). "AFP is a well-known cancer-specific marker, but AFP has no known function in healthy human beings." (PMID 21573244, 2011). "Rarely, extrahepatic AFP-producing hepatoid or nonhepatoid carcinomas, arising most commonly in the gastrointestinal tract, may occur." (PMID 21789263, 2011). "In addition, AFP is not always elevated in the early stages of cancer development, when therapy is mostly effective." (PMID 17244360, 2007). "Hypodifferentiated carcinoma of extrahepatic origin is usually arranged and presented in the form of islands or beams in the localized areas of histology, but immunohistochemistry does not express hepatocyte markers and does not show abnormally elevated serum AFP." (PMID 40740864, 2025). "Using the proposed device under the optimal conditions, alpha fetoprotein (AFP) and carcinoembryonic antigen (CEA) could be identified, with limits of detection of 136 pg/mL and 174 pg/mL, respectively, which are below the threshold values of these two cancer biomarkers for clinical diagnosis." (PMID 35600221, 2022). "Therefore, it is not surprising that the majority of clinical cancer biomarkers are glycoproteins, such as alpha-fetoprotein for liver cancer, cancer antigen 125 for ovarian cancer, carcinoembryonic antigen for colon cancer, and prostate-specific antigen for prostate cancer." (PMID 36125541, 2022). "Interestingly, in contrast to the results of the Hou, Luo, and Zhang meta-analysis, we found no AFP abnormalities in cancer subjects, which may suggest the need for screening tests adjusted to different populations." (PMID 32528895, 2020). "It is noted that in the case of patients with recurrent cancer, the sample size and difference between AFP and the Doylestown algorithm was large enough to provide >85% power and highlight the benefit in the use of the algorithm as opposed to AFP in this setting." (PMID 30169533, 2018). "Additionally, our study demonstrated that the AFP response could predict the prognosis of these patients in the absence of a radiological evaluation, especially in patients with diffuse malignant tumors that could not be evaluated by radiological criteria." (PMID 26831408, 2016). "Additionally, the AFP enhancer fragment may provide HCC-specific activity to the promoter of the non-tissue-specific, housekeeping phosphoglycerate kinase (pgk) gene, and this novel strategy may be useful for HCC-specific cancer gene therapy." (PMID 23173703, 2012). "The COMET‐LR identified 88.6% of AFP‐negative cancer cases and 85.7% of PIVKA‐II‐negative cancer cases." (PMID 40135830, 2025). "The classical circulating blood biomarkers for cancer, such as prostate-specific antigen (PSA), carcinoembryonic antigen (CEA), cancer antigen 125 (CA125), alpha-fetoprotein (AFP), etc., are neither sensitive nor specific." (PMID 40332502, 2025). "Particularly, relationships between AFP, ALB, CA125, and RBC, LYM, PCT, and TBIL values play an important role in distinguishing between cancer and non-cancer cases." (PMID 40943960, 2025).